RB1 (RB transcriptional corepressor 1)
Diseases named in the same sentence as RB1 in open-access papers (continued):
Sharing a sentence is not in itself a finding about the gene and the disease.
tumor (continued). "Research has demonstrated that, in addition to RB1 inactivation, RB creation and progression depend on epigenetic dysregulation of tumor-promoting pathways." (PMID 41002743, 2025). "The analysis revealed a hemizygous deletion characterized by an orange signal corresponding to the RB1 gene and two green centromere signals, indicating the presence of two chromosome copies in 36% of the analyzed tumor cells." (PMID 41230282, 2025). "To examine the effect of RB1 knockout on ccRCC tumor growth in vivo, we injected 786-O control and RB1 KO cells subcutaneously into the flanks of immunodeficient NOD-scid IL2Rgnull (NSG) mice." (PMID 40240354, 2025). "The RB1 gene functions as a tumor suppressor by inhibiting the G1/S transition through its interaction with E2F family transcription factors, which are commonly deleted in NEPC." (PMID 40746825, 2025). "AURKA, a kinase with roles in mitosis and cancer cell survival, contributed most significantly to RB1 tumour classification." (PMID 40775769, 2025). "Samples with a deep deletion exhibited the lowest median Rb protein abundance, and, as expected, the Rb abundance was proportional on average to the number of RB1 copies present in the tumor sample." (PMID 40138429, 2025). "The Rb protein family includes Rb1, p107, and p130, which are crucial factors involved in the induction of senescence and tumor suppression." (PMID 40643463, 2025). "Our current data confirm that these tumour suppressors are frequently disrupted by structural alterations, with pathogenic genomic events of any kind seen in 15% (NF1), 14% (PTEN) and 14% (RB1) of samples." (PMID 40593568, 2025). "Accordingly, liquid biopsy analysis comparing cfDNA from AH and plasma revealed a somatic RB1 splice-site variant c.1498+2T>C with a VAF of 98.5% only in AH, suggesting tumor biallelic inactivation." (PMID 41465072, 2025).
tumor (continued). "Previous research showed that RB1 plays a critical role in tumor suppression by promoting cell cycle exit, maturation, and maintenance of the terminally differentiated state in cardiomyocytes." (PMID 41462332, 2025). "The retinoblastoma protein 1 (RB1) is an important tumor suppressor that acts as a regulator of cell cycle progression via E2F TFs." (PMID 39860065, 2025). "Disruption of RB1 function permits re-entry into the cell cycle, enhancing plasticity and contributing to tumor heterogeneity." (PMID 41023204, 2025). "The proteins p16 and Rb1 work together as tumor suppressors, and disruption of their function is a common cause of cancer development." (PMID 40643463, 2025). "The frequent inactivation of RB1 during the tumor progression phase further complicates the landscape of how altered tumor metabolism contributes to the gain of malignant phenotypes." (PMID 40707487, 2025). "RB can be sporadic (60%) or hereditary with bilateral disease nearly always due to an inherited abnormal RB1 tumor-suppressor gene, while unilateral neoplasm is sporadic in 85% of cases." (PMID 39729290, 2025). "A number of imprinted tumor suppressor genes such as RB1, TP73, and CDKN1C showed copy number loss or the loss of expression in many tumor cell lines." (PMID 40414875, 2025). "RB1 VCN-01 is an oncolytic adenovirus designed to replicate in tumor cells that exhibit elevated levels of free E2F-1, a result of a dysfunctional pRB pathway." (PMID 41313526, 2025).
tumor (continued). "In vitro, PF-06873600 potently suppressed RB1 phosphorylation and inhibited cancer cell proliferation, while in vivo it achieved robust tumor regression, including approximately 90% reduction in OVCAR3 ovarian tumor xenografts at a single 50 mg/kg oral dose." (PMID 40949156, 2025). "Knockdown or functional inactivation RB1 in PCa cells prevents androgen-deprivation-induced proliferation arrest and promotes the growth of castration-resistant tumor xenografts." (PMID 39796175, 2025). "RB1 was the first tumor suppressor to be cloned and characterized, and it was later found to be defective in many human cancers in addition to retinoblastoma." (PMID 40199585, 2025). "C2 displayed amplifications in MYC and NOTCH2, potentially linked to aggressive tumor phenotypes, along with deletions in RB1 and CSMD1, which are associated with tumor suppressor loss." (PMID 41568381, 2025). "Even though RB is rare, scientists are interested in it since the RB1 is the first known tumor suppressor gene." (PMID 41002743, 2025). "Both mRNA and protein levels of RB1 were notably higher in tumour samples than in non‐cancerous tissues." (PMID 40070134, 2025). "A distinguishing feature is the loss of retinoblastoma protein (pRb) due to RB1 deletion, which aids in differentiation from similar-appearing neoplasms." (PMID 41527615, 2025). "In MPNSTs, the RB1 inactivation removes this checkpoint entirely, allowing continuous E2F activity, uncontrolled cell-cycle entry, and tumor growth." (PMID 41463204, 2025). "After categorizing cell lines into deletion and CN‐intact based on ploidy score, CN loss is commonly identified in these cell lines, and RB1‐deletion and NUDT15‐deletion are largely matched, consistent with the observation in patient tumor samples." (PMID 40904703, 2025).
tumor (continued). "RB1, the first human tumour suppressor gene identified, plays a pivotal role in cell cycle regulation by interacting with the transcription factor E2F1, leading to G1‐S checkpoint arrest and suppression of tumorigenesis." (PMID 40070134, 2025). "As expected, Pten−/−; Rb1−/− tumours grew significantly larger than Pten−/−; Rb1+/+ tumours at the 13-week time point." (PMID 38654015, 2024). "Introduction of exogenous Rb1 into tumor cells can inhibit growth, proliferation, anchorage-independent colony formation and tumorigenicity in mice." (PMID 38339234, 2024). "It remains possible that the combined inactivation of RB1 and HR genes contributes to enhanced chemotherapy response and/or an impaired ability for tumor cells to develop therapy resistance." (PMID 38837893, 2024). "We also compared the expression profile of data sets of two patient-derived MYCNA tumours, one RB1 proficient; GSE161449 and one RB1 deficient; OEP 000103." (PMID 37606819, 2024). "RB is caused by the biallelic deletion of the tumour suppressor gene RB transcriptional co‐repressor 1 (RB1) in 98% of cases, whereas 2% of cases have normal RB1 levels in tumours initiated by amplification of the MYCN oncogene." (PMID 38613348, 2024). "In vivo experiments have shown that if tumor cells originally have RB1 (gene of Rb protein) depletion, this Rb status will be obligatory for the further growth and survival." (PMID 38279263, 2024). "Among these, the RB1 gene is a critical tumor suppressor with a significant role in the pathogenesis of MM." (PMID 39664374, 2024). "Tumors with RB1 biallelic inactivation were found to upregulate expression of TME-enriched lncRNAs, which were correlated with a tumor-intrinsic signature of RB1 loss and also associated with poor outcomes." (PMID 38396008, 2024). "Previous studies have identified specific mutation types associated with tumor sensitivity to AURKA inhibitors, such as RB1 deficiency or loss of SMARCA4 or ARID1A." (PMID 38521813, 2024). "Other genes rarely change except for RB1 inactivation, which is correlated to a differentiated tumor-expressing mature cone marker, called RB subtype 1." (PMID 38920989, 2024). "In certain types of tumors, inactivation of RB1 leads to both a disruption of cell cycle regulation, which facilitates initial tumor growth, and a disruption of cell-to-cell contacts." (PMID 38672640, 2024). "As the first cloned tumor suppressor gene, numerous studies have documented the anti-proliferative function of Rb1 in the nervous system." (PMID 38637503, 2024).
tumor (continued). "RB1 was one of the first tumor suppressors to be identified and is a master regulator of cell cycle progression." (PMID 38424044, 2024). "The retinoblastoma protein 1 (RB1), a notable tumor suppressor, plays a pivotal role in cell-cycle checkpoints and limits cell cycle progression." (PMID 38822363, 2024). "CDK4 and CDK6 play a key role in mammalian cell proliferation by working in complex with CCND1 to phosphorylate and inhibit RB1 tumor-suppressor activity during early G1 phase." (PMID 38507413, 2024). "Research indicates that irreversible impairments in the functions of the RB1 tumor suppressor frequently predict poor prognoses in cancer patients." (PMID 38672640, 2024). "Understanding the complex interplay between RB1 and cellular pathways is beneficial to fully elucidate its tumor-suppressive role across different cancer types and for therapeutic development." (PMID 38672640, 2024). "For example, retinoblastoma-associated protein (RB1), a predicted substrate of TRIM33, is a key tumor suppressor to regulate the G1/S transition of the cell cycle." (PMID 39062881, 2024). "Indeed, in animal models, the origin of the tumor is attributed to Müller glial cells, amacrine, or horizontal cells, while in the human retina, it seems involve cone precursors, as also supported by studies conducted with the use of ROs derived from hESCs mutated on the RB1 gene." (PMID 38396799, 2024). "As a tumor suppressor, P16 simultaneously inhibits RB1 phosphorylation and destabilizes RB1 via UTP14a-catalyzed K810 ubiquitination." (PMID 39351198, 2024). "The high protein levels of CCND1 and RB1 hyperphosphorylation in long-term FLCN knockdown HK2 tumor spheroids likely contributes to their observed tumorigenicity." (PMID 38978568, 2024). "Studies of RB1-related pathways have revealed striking similarities in the DNA sequence characteristics across tumor types with diverse genetic and epigenetic profiles." (PMID 39664374, 2024). "We reasoned that there are co-alterations that coordinate with NKX3-1 and RB1 losses to drive tumor progression, and we can use ProstaMine to find these co-alterations." (PMID 38751776, 2024). "While a histological analysis indicated that Rb1 expression was markedly reduced in both normal and tumor specimens from the High Myc mice compared with the Pbsn-cre mice, the expression of Myc and Klhl42 was significantly increased in the High Myc mice." (PMID 38424044, 2024).